RNASEH2B (ribonuclease H2 subunit B)
Description:
Non catalytic subunit of RNase H2, an endonuclease that specifically degrades the RNA of RNA:DNA hybrids. Participates in DNA replication, possibly by mediating the removal of lagging-strand Okazaki fragment RNA primers during DNA replication. Mediates the excision of single ribonucleotides from DNA:RNA duplexes.
Synonyms: AGS2; DLEU8; FLJ11712
Tractability: PROTAC: ubiquitination databases record sites on it; its protein half-life has been measured.
Gene: Protein-coding gene on chromosome 13 (50,909,747 to 51,024,120, forward strand). Ensembl gene ENSG00000136104.
Subcellular location: Nucleus
Subcellular location (Human Protein Atlas): Nucleoplasm
Gene Ontology:
Molecular function: protein binding
Biological process: RNA catabolic process; mismatch repair
Cellular component: nucleoplasm; ribonuclease H2 complex; nucleus
Genetic constraint (gnomAD): Loss-of-function variants: 10 observed, 12.08 expected, observed/expected ratio (o/e) 0.83, 90% interval 0.51 to 1.4. The upper end of that interval is the gene's LOEUF score, 1.4, which puts it in group 5 of 6, group 1 being the genes least tolerant of losing a copy. Missense variants: 208 observed, 180.74 expected, observed/expected ratio (o/e) 1.15, 90% interval 1.03 to 1.29. Synonymous variants: 59 observed, 65.13 expected, observed/expected ratio (o/e) 0.91, 90% interval 0.73 to 1.12.
Gene-disease validity (ClinGen):
ClinGen rates the evidence that RNASEH2B causes each of these diseases.
RNASEH2B-related type 1 interferonopathy (autosomal recessive): Definitive. Any type 1 interferonopathies in which the cause of the disease is a variation in the RNASEH2B gene.
Homologues: Orthologues: chimpanzee RNASEH2B (99% identical), macaque RNASEH2B (93% identical), pig RNASEH2B (85% identical), guinea pig RNASEH2B (83% identical), mouse Rnaseh2b (81% identical), rat Rnaseh2b (80% identical), dog RNASEH2B (68% identical), rabbit RNASEH2B (60% identical), tropical clawed frog rnaseh2b (55% identical), zebrafish rnaseh2b (46% identical), Drosophila melanogaster CG11164 (28% identical), Caenorhabditis elegans F21D5.6 (21% identical).
Diseases named in the same sentence as RNASEH2B in open-access papers:
RNASEH2B is named in the same sentence as 68 diseases in open-access papers, as found by Europe PMC text mining. Sharing a sentence is not in itself a finding about the gene and the disease. The quoted sentences say what the papers report.
Aicardi-Goutières syndrome (19 papers, 2014 to 2025). "RNASEH2B, linked to Aicardi-Goutières syndrome 2, was found in three patients who shared the same mutation and exhibited similar clinical features, including pyramidal syndrome, dystonia, and psychomotor delay." (PMID 40388540, 2025). "While damaging biallelic variants in RNASEH2B often result in Aicardi–Goutières Syndrome (AGS), our patient lacks such biallelic variants and does not exhibit AGS symptoms." (PMID 40565278, 2025). "We report a case of severe Aicardi–Goutières syndrome caused by a novel homozygous RNASEH2B intronic variant, NC_000013.10(NM_024570.4):c.65-13G > A p.Glu22Valfs*5." (PMID 39183359, 2024). "The two couples were carriers of pathogenic variants in the MYO7A gene (Usher syndrome) and RNASEH2B (Aicardi-Goutières syndrome)." (PMID 36406136, 2022). "Mutations in the genes encoding RNaseH2B subunits cause the Aicardi-Goutières syndrome (AGS), a neurological inflammatory disorder found in children." (PMID 25423901, 2014). "In addition, Jafarpour described a de novo mutation in RNASEH2A, which is one of the genes, along with SAMHD1 (case 12) and RNASEH2B (sibling of case 13) that can cause Aicardi-Goutières Syndrome (AGS), a type 1 interferonopathy, autoinflammatory disorder." (PMID 40894167, 2025). "We report the treatment response to baricitinib, a JAK‐inhibitor, in a 4‐year‐old girl affected by Aicardi‐Goutières syndrome (AGS2, RNASEH2B mutation)." (PMID 37534202, 2023). "Aicardi-Goutieres syndrome (AGS) is an early-onset encephalopathy that can be caused by a gene mutation in one of 7 discovered genes so far (TREX1, RNASEH2B, RNASEH2C, RNASEH2A, SAMHD1, ADAR1, and IFIH1)." (PMID 32737687, 2020). "In the severe neuroinflammatory disorder Aicardi-Goutières syndrome, more than 50% of total AGS patients have biallelic mutations in one of the three genes encoding RNase H2: 5% for RNASEH2A, 36% for RNASEH2B, and 12% for RNASEH2C." (PMID 32069311, 2020). "The genetic dissection of a particular type I interferonopathy, Aicardi-Goutières syndrome, initially described as an early-onset progressive brain disease, identified mutations of the TREX1, RNASEH2A, RNASEH2B, RNASEH2C, SAMHD1, ADAR, and MDA5 genes as causal." (PMID 27190218, 2016). "Aicardi-Goutieres syndrome is classified as a monogenic interferon disease resulting from an aberrant mechanism involving intracellular nucleic acid sensing mediated by TREX1, RNASEH2A, RNASEH2B, RNASEH2C, SAMHD1, ADAR1 or IFIH1." (PMID 39286150, 2024).
prostate carcinoma (6 papers, 2020 to 2026). A carcinoma that arises from epithelial cells of the prostate gland. "The current study reports on RNASEH2B protein loss in advanced prostate cancer and its association with RB1 protein loss, clinical outcome, and clonal dynamics during treatment with PARP inhibition in a prospective clinical trial." (PMID 38833311, 2024). "PARP inhibitor treatment clears subclones with RNASEH2B loss in metastatic castration-resistant prostate cancer, imparting clinical benefit in a subset of patients." (PMID 38833311, 2024). "In that report, deleterious GVs in the AGS genes ADAR and RNASEH2B were detected in families and patients with astrocytomas or glioblastomas as well as with prostate cancer." (PMID 41546701, 2026). "Specifically RNASEH2B deletions were reported in 57% of chronic lymphocytic leukemias and 36% of aggressive prostate cancers." (PMID 33353557, 2020). "Two loci on chromosome 13q14 frequently lost in those cancer types (microRNA cluster DLEU2‐mir‐15‐16 in CLL, and RB1 locus in prostate cancer) are located in close proximity to the RNASEH2B gene." (PMID 31833079, 2020). "Interestingly, the expression of RNASEH2A was found to be upregulated in CRPC, while that of RNASEH2B was downregulated in prostate cancer according to the publicly available database, as observed in a previous study." (PMID 36923313, 2022). "Interestingly, an exome sequencing study of 491 cases has proposed RNASEH2B as a candidate gene for prostate cancer." (PMID 33353557, 2020). "Determination of RNASEH2B copy numbers in 100 patient‐derived CLL cell lines and 226 prostate cancers showed that at least one copy was lost in 57% and 36% of the respective cancer samples." (PMID 31833079, 2020).
Aicardi-Goutières syndrome 2 (3 papers, 2014 to 2025). "RNASEH2B loss-of-function mutations cause Aicardi-Goutieres syndrome type 2 in humans (AGS2, OMIM 610181)." (PMID 24391517, 2014).
ovarian carcinoma (3 papers, 2020 to 2023). A malignant neoplasm originating from the surface ovarian epithelium. "We report one patient with a truncating variant in RNASEH2B whose longer survival appears consistent with the association of RNASEH2B mRNA levels and prolonged survival in previously published ovarian cancer cohorts." (PMID 33353557, 2020). "In RNASEH2B, one truncating variant, p.C44X, was detected in a single ovarian cancer patient." (PMID 33353557, 2020). "Data mining via the TumorPortal indicates four truncating or splice variants of RNASEH2B in epithelial cancers (2 in lung adenocarcinoma, 1 in melanoma and 1 in endometrial carcinoma) but none among 316 ovarian cancers." (PMID 33353557, 2020).
chronic lymphocytic leukemia (2 papers, 2020 to 2021). "Alternately, homozygous deletion of RNASEH2B has been shown to occur in chronic lymphocytic leukemia (CLL) and other malignancies, Similarly, pathogenic mutations in SAMHD1 have been reported in up to 11% of CLL patients." (PMID 33717156, 2021).
colorectal tumor (2 papers, 2021 to 2024). "Increased RNASEH2B expression has also been shown to correlate with metastasis in colorectal tumors." (PMID 38725628, 2024).
lupus (2 papers, 2022 to 2025). "The genetic analysis detected at least one variant in 11 (26.1%) children, 5 (45.4%) with cSLE (ADAR, TNFAIP3, RNASEH2B, SHOC2, IFIH1) and 6 (54.5%) with lupus-like phenotype (TREX, DNASE1,RNASEH2B, C1S, TLR7, STAT5A, TNFRSF13B)." (PMID 36096831, 2022).
Autoimmunity (1 paper, 2025). The occurrence of an immune reaction against the organism's own cells or tissues. "This current study shows the genetic changes in genes related to autoimmunity such as pathogenic variants of IL36RN, RNASEH2B, and SLC29A3 genes." (PMID 39992598, 2025).
Cerebral atrophy (1 paper, 2021). Atrophy (wasting, decrease in size of cells or tissue) affecting the cerebrum. "Aicardi-Goutières (AGS) is a rare immune dysregulated disease due to mutations in TREX1, RNASEH2A, RNASEH2B, RNASEH2C, SAMHD1, ADAR1 or IFIH1, characterized by encephalopathy, dystonia, basal ganglia calcifications, white matter abnormalities, and cerebral atrophy." (PMID 33482855, 2021).
cervical cancer (1 paper, 2021). A primary or metastatic malignant neoplasm involving the cervix. "This notion was also suggested by others showing that knocking out RNASEH2A in cervical cancer HeLa cells results in an increased sensitivity to ataxia telengiectasia and Rad3-related (ATR) inhibitors compared to knocking out RNASEH2B." (PMID 33805806, 2021).
colon cancer (1 paper, 2024). "This study revealed that remimazolam promoted the cell-cycle progression and proliferation of HCT8 colon cancer cells by upregulating CDK1, PTTG1, CDC25C, CDK4, PLK1, PCNA, Ki67, RNASEH2B, FEN1, Cyclin D1,CD44 CDK2, CDKN3, CDC45, IQGAP3, and CDK6." (PMID 38725628, 2024).
colorectal cancer (1 paper, 2019). A primary or metastatic malignant neoplasm that affects the colon or rectum. "In colorectal cancer, RNASEH2C mRNA was found to be reduced in tumor tissue compared to normal, while increased expression of RNASEH2B and RNASEH2C was correlated with metastasis, like in our study." (PMID 31125342, 2019).
Constipation (1 paper, 2025). Infrequent or difficult evacuation of feces. "ENALA treatment for 24 h upregulated RNASEH2B, which is associated with headache and glucose intolerance, and downregulated FBXW7 (F-box and WD repeat domain containing 7), which is associated with constipation, through miRNA regulation." (PMID 40940770, 2025).
developmental delay (1 paper, 2021). "A child (ID 42) with a homozygous missense variant in the Aicardi-Goutieres syndrome-associated gene, RNASEH2B, presented with optic atrophy, developmental delay, abnormal MRI and seizure onset at 36 months." (PMID 34469436, 2021).
gastric adenocarcinoma (1 paper, 2019). "Similarly, analysis of overexpressed genes in gastric adenocarcinoma revealed increased expression of RNASEH2B." (PMID 31125342, 2019).
Hemophagocytic lymphohistiocytosis (1 paper, 2021). "This patient was the focus of our 2020 MODS paper, where we discovered the 16 yo patient to have Hemophagocytic lymphohistiocytosis (HLH) likely driven by a dominant-negative splicing variant in RNASEH2B that is activated by the EBV suppression of nonsense-mediated decay." (PMID 34925370, 2021).
intestinal tumors (1 paper, 2022).
pancreatic cancer (1 paper, 2025). "Again, deletion of RNASEH2B was demonstrated to synergize with PARP inhibition in preclinical pancreatic cancer models." (PMID 39968096, 2025). "Public genomic databases of pancreatic cancer revealed that RNASEH2B is commonly co-deleted with retinoblastoma 1 (RB1) and BRCA2, three closely located genes on chromosome 13q." (PMID 39968096, 2025).
squamous cell carcinoma (1 paper, 2019). A carcinoma arising from squamous epithelial cells. "Rnaseh2b inactivation in the epidermis also resulted in increased proliferation, DNA damage, and development of squamous cell carcinoma." (PMID 31125342, 2019).
cancer (9 papers, 2011 to 2025). A tumor composed of atypical neoplastic, often pleomorphic cells that invade other tissues. "The determination of RNASEH2B copy numbers in human cancer can become significant in the context of therapy, because RER‐deficient cells are sensitive to (poly‐ADP)ribose polymerase (PARP) inhibition." (PMID 31833079, 2020). "We first screened the messenger RNA (mRNA) expression of the nucleotide degrading enzyme genes TREX1, SAMHD1, RNASEH2A, RNASEH2B, and RNASEH2C in 14 cancer types using TCGA RNAseq data." (PMID 29843367, 2018). "Using inducible non-cancer and cancer cell models, we show that overexpression of the RNASEH2B subunit can increase protein levels and activity of the entire RNase H2 complex." (PMID 40640336, 2025). "PARP inhibitors were also tested in RNASEH2B deleted cancers, in HER negative cancers, in few cases—as the pretreatment with adjuvant taxanes or anthracycline." (PMID 34639169, 2021). "RNASEH2B loss does not impair HR and is synthetically lethal with BRCA1 deficiency, indicating that the distinct mechanisms of PARP inhibitor sensitivity may be differentially affected by the genetic landscape of the particular cancer." (PMID 38201511, 2023).
tumor (4 papers, 2019 to 2025). "The degree of benefit imparted is likely dependent on the proportion of tumor impacted by RNASEH2B loss as well as the molecular makeup of the tumor subclones that are not being cleared." (PMID 38833311, 2024). "Of the 2–5 bp deletions in tumours with biallelic RNASEH2B loss, more than half (57%) were 2 bp deletions, which were predominantly at STR and SNMH sequences and substantially enriched for the TNT motif, consistent with the ID-TOP1 mutational signature." (PMID 35140396, 2022). "PARP inhibition may benefit men suffering from mCRPC by eradicating tumor subclones with RNASEH2B loss." (PMID 38833311, 2024). "R-loop accumulation can thereby increase anti-tumour immunity and enhance immune checkpoint blockade (ICB) responses, which RNASEH2B overexpression can attenuate." (PMID 41378389, 2025).
inflammatory myopathy (1 paper, 2022). "In agreement, both TREX1 and RNASEH2B deficiencies have been clinically associated with inflammatory symptoms such as inflammatory myopathy and systemic inflammation." (PMID 35262626, 2022).
RNASEH2B also shares sentences with these, for which no sentence is quoted: acute myeloid leukemia (1 paper); Arthritis (1); astrocytomas (1); Ataxia (1); autoimmune disease (1); Blau syndrome (1); brain disease (1); chronic kidney disease (1); complement deficiencies (1); diabetes (1); diabetes retinopathy (1); Dystonia (1); Encephalopathy (1); endometrial carcinoma (1); epilepsy (1); Failure to thrive (1); familial cold autoinflammatory syndrome (1); familial Mediterranean fever (1); gestational diabetes (1); glioblastoma (1); Glucose intolerance (1); Headache (1); hemophilia A (1); hereditary cancer (1); hereditary spastic paraplegia (1); Histiocytosis (1); Hypertension (1); hypertrichosis (1); hypertrophic cardiomyopathy (1); infection (1).
A further 16 diseases each share a sentence with RNASEH2B in 1 paper.